EPCAM (epithelial cell adhesion molecule)
Diseases named in the same sentence as EPCAM in open-access papers (continued):
Sharing a sentence is not in itself a finding about the gene and the disease.
primary biliary cirrhosis (3 papers, 2015 to 2024). "H19 was markedly upregulated in primary sclerosing cholangitis and primary biliary cirrhosis, which prevented zinc finger E‐box binding homeobox 1 (ZEB1) inhibition of epithelial cell adhesion molecule (EpCAM), causing EpCAM activation and contributing to biliary hyperplasia." (PMID 37398637, 2023).
rectal tumor (3 papers, 2010 to 2025). "Our finding of abundant expression of CEA, c-MET, and EpCAM in most rectal tumors corroborates previous large-scale studies." (PMID 40563608, 2025). "Among the markers assessed, CEA, EpCAM, and c-MET demonstrated significant overexpression in rectal tumors." (PMID 40563608, 2025).
salivary gland cancer (3 papers, 2014 to 2023). A primary or metastatic malignant neoplasm that affects the major or minor salivary glands. "Different subtypes of salivary gland cancer can have different molecular profiles, resulting in different levels of EpCAM expression." (PMID 37627911, 2023). "The expression of EpCAM in salivary gland cancer shows variability, with some cases demonstrating overexpression while others exhibit lower levels." (PMID 37627911, 2023). "This article aims to provide a comprehensive overview of the differential expression of EpCAM in salivary gland cancer and its potential correlation with the biological behavior of these tumors." (PMID 37627911, 2023). "Overall, out of 65 malignant neoplasms of the salivary glands, the evaluation regarding the expression of EpCAM was positive in 81.5%, with diversity regarding the proportion score (PS), intensity score (IS), and total immunostaining score (TIS)." (PMID 37627911, 2023). "Among the many biomarkers under investigation, epithelial cell adhesion molecule (EpCAM) has emerged as a promising candidate in salivary gland cancer research." (PMID 37627911, 2023). "In conjunction with our data, it should be of interest in future studies to investigate the functional involvement of hypertrimethylated H3K9 on EpCAM and other tumor suppressor genes in relation to progression of salivary gland cancers." (PMID 36064736, 2022).
(CMMRD) syndrome (2 papers, 2022 to 2025).
adenocystic carcinomas (2 papers, 2019 to 2023). "In contrast, a statistically significant association between strong EpCAM expression and tumor aggressiveness was observed in both mucoepidermoid and adenocystic carcinomas in our study." (PMID 37627911, 2023). "We explore the differential expression of EpCAM in different histologic subtypes of salivary gland malignancies, including adenoid cystic carcinoma, mucoepidermoid carcinoma, acinic cell carcinoma, and others." (PMID 37627911, 2023). "Of course, in this study, the authors only examined the expression of EpCAM in adenoid cystic carcinoma." (PMID 37627911, 2023). "EpCAM expression has been shown in 97.6% of adenoid cystic carcinomas and its intensity is correlated with a poor prognosis but it cannot be used for a differential diagnosis on cytological samples." (PMID 31805712, 2019). "They showed that reduced EpCAM expression was associated with aggressive features in mucoepidermoid carcinoma, whereas adenocystic carcinoma (AdCC) showed negative or weakly positive EpCAM immunoreactivity." (PMID 37627911, 2023).
alcoholic hepatitis (2 papers, 2021 to 2023). Acute hepatitis resulting from ingestion of alcohol. "When EpCAM was knocked down, the PI3K/Akt/mTOR signaling pathway was arrested, and the level of liver fibrosis in alcoholic hepatitis mice was improved." (PMID 36990999, 2023). "Our observation seems to be in agreement with Sancho-Bru and co-workers’ report of lack of correlation between EpCAM gene expression and MELD score in patients with alcoholic hepatitis." (PMID 35070966, 2021).
ameloblastoma (2 papers, 2017 to 2022). The most common odontogenic tumor, arising from the epithelial component of the embryonic tooth and usually affecting the molar-ramus region of the mandible or maxilla. "Recent research conducted by Sook & Keun (2014) to compare protein expression between intraoral BCC and peripheral ameloblastoma detected with 50 different types of antisera also showed that intraoral BCC showed strong positive results against EpCAM." (PMID 29464122, 2017).
astrocytoma (2 papers, 2020 to 2025). "The activity of DARPin-IRDye 700DX conjugates was assessed towards OVCAR-3, OV90, SKOV-3 and EpCAM-negative E98 astrocytoma cells." (PMID 32630661, 2020). "No significant toxicity was observed in EpCAM-negative E98 astrocytoma cells." (PMID 32630661, 2020).
bile duct carcinoma (2 papers, 2022 to 2024). "Epithelial cell adhesion molecule (EPCAM) is a surface biomarker of tumor stem cells in bile duct carcinoma that is highly expressed in CCA." (PMID 36300097, 2022).
bladder tumor (2 papers, 2017 to 2024). "EpCAM showed a high sensitivity (95%) and specificity (100%) in lymph nodes and also a high sensitivity (92%) in the primary bladder tumor." (PMID 28820475, 2017). "EpCAM expression in lymph nodes was compared to the expression of EpCAM in the matched primary bladder tumor." (PMID 28820475, 2017). "In the current study, the expression of EpCAM in lymph node metastases of UCC of the bladder was compared to the expression of EpCAM in matched lymph nodes without metastases and to the expression of EpCAM in the matched invasive primary bladder tumor." (PMID 28820475, 2017).
cancerous peritonitis (2 papers, 2021 to 2025). "EpCAM/LVRN double‐positive cells were also observed both in CTCs and ascitic cells from cancerous peritonitis." (PMID 41024351, 2025).
cervical intraepithelial neoplasia (2 papers, 2016 to 2017). "The level of EpCAM expression and the number of positive cells has been found to increase with the grade of carcinogenesis in cervical intraepithelial neoplasia." (PMID 26984381, 2016).
cervical tumor (2 papers, 2017 to 2025). "Expression of EpCAM in cervical tumor cells was validated using tumor cell lines, though not all epithelial cancer cell lines express it." (PMID 41154384, 2025).
cholestasis (2 papers, 2022 to 2024). Impairment of the bile flow caused by obstruction within the liver, or outside the liver in the bile duct system. "Q-EpCAM was the only immunohistochemical marker showing a correlation with ALP, a marker of cholestasis, and was related to a potentially worse prognosis since both EpCAM and ALP independently correlated either with fibrosis stage 4." (PMID 38398042, 2024). "The hepatic progenitor markers EPCAM seems to increasingly overlap with LPLCs as cholestasis progresses, especially in the adjacent central vein." (PMID 35313986, 2022). "Noteworthily, we found a correlation between biochemical cholestasis, indicated by the increase of ALP values, and the EpCAM expression with the presence of immature “intermediate hepatocytes”." (PMID 38398042, 2024).
choriocarcinoma (2 papers, 2020 to 2023). An aggressive malignant tumor arising from trophoblastic cells. "EpCAM has also been reported to be positive in choriocarcinoma." (PMID 37957624, 2023). "We demonstrate that the Epithelial Cell Adhesion Molecule (EpCAM) is broadly expressed in GCT cell lines of different histologic origin including seminoma, choriocarcinoma (CHC), and embryonal carcinoma (EC)." (PMID 32438548, 2020). "EpCAM positivity is close to 100% in GCT cell lines of different histology derived from seminoma (TCam-2), choriocarcinoma (JAR), and embryonal carcinoma (2102Ep and GCT27)." (PMID 32438548, 2020).
chromophobe carcinoma (2 papers, 2010 to 2020). "Homogeneous epithelial cell adhesion molecule (EpCAM) expression confirms the diagnosis of chromophobe carcinoma rather than oncocytoma." (PMID 20205900, 2010).
chronic myelogenous leukemia (2 papers, 2021 to 2023). "Clinical trials employing anti-EpCAM have shown tumor suppression in colon and prostate cancer, and an anti-CD123 scFv-pseudomonas exotoxin exhibited cytotoxic effects on AML and chronic myeloid leukemia (CML) tumor cells." (PMID 37784157, 2023).
clear cell carcinoma (2 papers, 2020 to 2023). "A previous study reported a lower percentage of EpCAM-positive EVs released from another HGSOC cell line (~24 %, OVCAR-3), an endometrioid cell line (~18%, ES-2) and a clear cell carcinoma cell line (~15%, IGROV) detected by fluorescent-NTA." (PMID 37375854, 2023).
colorectal adenoma (2 papers, 2012 to 2013). An adenoma that arises from the colon or rectum. "Moreover, Huth and his team reported a lack of EPCAM protein expression in a colorectal adenoma, suggesting that EPCAM immunohistochemistry may detect EPCAM deletions already at a precancerous stage." (PMID 23938213, 2013).
craniopharyngioma (2 papers, 2016 to 2022). A benign, partly cystic, epithelial tumor of the sellar region, presumably derived from Rathke pouch epithelium. "Research has shown that epithelial cell adhesion molecule (Ep-CAM) expression in craniopharyngioma could be a predictive marker of relapse." (PMID 36387067, 2022).
cutaneous melanoma (2 papers, 2015 to 2019). A primary melanoma arising from atypical melanocytes in the skin. "A series of 23 patients with cutaneous melanoma, a cell type that does not express EpCAM, revealed the utility of the ScreenCell® Cyto device for enumeration of CTCs, cytological analysis, and analysis of genetic mutations." (PMID 31370190, 2019). "This device is further tested by Desitter group in enumeration of CTCs from 23 cutaneous melanoma patients (CTCs does not express EpCAM) for the purpose of cytological analysis and analysis of genetic mutations." (PMID 25977918, 2015).
emphysema (2 papers, 2018 to 2025). "Similarly to smokers, the aging microenvironment is associated with a significant decrease of the EpCAM+ epithelial cell layer that correlates with emphysema and decreased gas exchange surface." (PMID 30090106, 2018). "Overall, our findings indicate that lung EpCAM+ epithelial cells and CD31+ blood endothelial cells are the major sources of G-CSF in lung epithelial/stromal cells when stimulated with IL-17A, which plays a pivotal role in the development of Siglec-F+ neutrophils in PPE-induced emphysema mice." (PMID 40461699, 2025).
epithelial dysplasia (2 papers, 2017 to 2020). "Loss of EpCAM expression in IEC resulted in epithelial dysplasia and comprised barrier function that manifested as a severe congenital diarrheal syndrome termed CTE." (PMID 32781650, 2020). "Our data suggest that EpCAM modulation protects against epithelial dysplasia and stabilizes human tissue architecture." (PMID 28084299, 2017).
fatty liver (2 papers, 2014 to 2016). "Our serum FGF19 data consist to expressions of FGF19/FGFR4 and EpCAM in tissue distributions, and provide further evidence for FGF19 as a marker to evaluate the risk of HCC in patients with fatty liver disease." (PMID 27447573, 2016). "The aim of this study is to investigate the molecular components of the signaling pathways that are responsible for the development and progression of HCC and to provide the evidence for the clinical activity of FGF19, FGFR4, and EpCAM in patients with HCC arising from fatty liver disease." (PMID 27447573, 2016). "Moreover, the number of EpCAM-positive HPCs was strictly correlated with NAS (r = 0.606; p<0.01) and PNHS scores (r = 0.595; p<0.01), with hepatic steatosis (r = 0.499; p<0.05) and ballooning (r = 0.683; p = 0.01) but not with fibrosis or lobular inflammation." (PMID 24505350, 2014).
germ cell tumor (2 papers, 2013 to 2024). A benign or malignant, gonadal or extragonadal neoplasm that originates from germ cells. "Based on these findings, EpCAM is under evaluation as a therapeutic target in germ cell tumors and has been used to identify circulating germ cell tumor cells in the blood." (PMID 38786342, 2024).
Hepatitis (2 papers, 2016). Inflammation of the liver. "Treatment of EpCAM positive tumor patients with catumaxomab caused dose dependent hepatitis as evidenced by significant elevations in serum alanine- and aspartate aminotransferases, bilirubin, γGT and induction of the acute phase C-reactive protein (CRP) and the cytokines IL6 and IL8." (PMID 27058902, 2016). "The elevated mRNA levels of EpCAM, S100A4, Twist, or Snail were firstly confirmed in mild hepatitis and showed a positive relationship with inflammation severity." (PMID 27881141, 2016).
hepatitis B (2 papers, 2016 to 2019).
hepatitis C (2 papers, 2016 to 2022). "Some examples, including ADA for adult T-cell leukemia (ATL), CD3D for T1DM and EPCAM for hepatitis C (HC), are known target–disease associations, indicating that our proposed method can accurately predict known therapeutic indications." (PMID 35758779, 2022).
kidney tumor (2 papers, 2020 to 2021). "Our data show that EpCAM expression in kidney tumor tissues was principally not stronger than in normal tissue." (PMID 33276608, 2020). "Thus, in line with previous studies, which showed that normal kidney cells express CD10, HLA-DR, and low EpCAM levels, these markers were also expressed here on all benign (but not malignant) kidney tumors." (PMID 34638431, 2021).
Lewis lung carcinoma (2 papers, 2020 to 2024). "Red fluorescent EpCAM-transduced Lewis lung carcinoma cells (EpCAM/tdtLL/2 cells) were implanted intracranially." (PMID 39358663, 2024).
mucinous ovarian carcinomas (2 papers, 2021 to 2024). An invasive malignant neoplasm that arises from the ovary and is characterized by the presence of malignant epithelial cells that contain intracytoplasmic mucin and may resemble the epithelial cells of the endocervix or gastrointestinal tract. "Taking into account that high overexpression of EpCAM is observed in 85% of mucinous ovarian carcinomas and in 90% of ovarian clear cell carcinomas, there must be tumors of these histotypes with high levels of both HER2 and EpCAM expression." (PMID 34439094, 2021).
nasal polyps (2 papers, 2020 to 2026). "Specific biomarkers, such as E-cadherin and EpCAM for epithelial cells and vimentin and N-cadherin for mesenchymal cells, have been identified as markers of EMT activity within nasal polyps 5-8." (PMID 41583532, 2026). "During the development of nasal polyps, EMT leads to a shift from epithelial characteristics to mesenchymal traits, characterized by a decrease in epithelial markers (E-cadherin and EpCAM) and an increase in mesenchymal markers (vimentin, FBN, and N-cadherin) 5-8." (PMID 41583532, 2026).
non-alcoholic fatty liver disease (2 papers, 2020 to 2024). "Moreover, EpCAM expression is found to be positively associated with the progression of nonalcoholic fatty liver disease (NAFLD)." (PMID 38791091, 2024). "There is no previous study to investigate EpCAM-expressing CSCs for their tumorigenic ability in a compromised liver microenvironment such as non-alcoholic fatty liver disease (NAFLD)." (PMID 32547703, 2020).
non-Hodgkin lymphoma (2 papers, 2009 to 2020). Distinct from Hodgkin lymphoma both morphologically and biologically, non-Hodgkin lymphoma (NHL) is characterized by the absence of Reed-Sternberg cells, can occur at any age, and usually presents as a localized or generalized lymphadenopathy associated with fever and weight loss. "Ten years later, a BsAb (anti-CD19 × anti-CD3) was studied in a clinical trial for the treatment of non-Hodgkin’s lymphoma (NHL) and it took until 2009 for the approval of catumaxomab (anti-epCAM × anti-CD3) for the treatment of patients with malignant ascites." (PMID 32457743, 2020).
oropharyngeal carcinoma (2 papers, 2018 to 2019). Carcinoma, predominantly squamous cell, arising from the epithelial cells of the oropharynx. "In order to exclude a confounding impact of sublocalizations of tumors on the clinical outcome of the four EGFR/EpCAM patient subgroups, we analyzed the most prominent entity, i.e., oropharyngeal carcinomas (n = 105)." (PMID 30261040, 2018).
ovarian adenocarcinoma (2 papers, 2013 to 2015). An adenocarcinoma that arises from the ovary. "Further characterization of SCCOHT-1 and BIN-67 cells by cell surface markers including CD90 and EpCAM demonstrated similar patterns with differences to the ovarian adenocarcinoma cells." (PMID 26436697, 2015). "Differences in the CD90 and EpCAM mRNA transcripts between the ovarian adenocarcinoma NIH:OVCAR-3 and SK-OV-3 compared to BIN-67 and SCCOHT-1 cells and associated in vivo tumors substantiated the special entity of SCCOHT tumors." (PMID 26436697, 2015). "In this regard, the expression of EpCAM has been shown to occur in almost all adenocarcinomas, including ovarian adenocarcinomas." (PMID 24137345, 2013).
pheochromocytoma (2 papers, 2008 to 2021). "The only pheochromocytoma analyzed (n = 1) showed a distinct CD56++ CD57+ GD2++ CD271+ CD9+ CD81+ CD90het CD58+ phenotype, in the absence of expression of CD10, CD99, CD117, EpCAM, nuMyoD1, and numyogenin." (PMID 34638431, 2021).
pituitary adenoma (2 papers, 2021 to 2025). "As a result, we observed 84–98% of EpCAM-positive cells and 7–13% of CD44-positive cells, suggesting that most of the population belongs to the pituitary adenoma cells." (PMID 40002253, 2025).
polyp (2 papers, 2023 to 2024). A usually exophytic mass attached to the underlying tissue by a broad base or a thin stalk. "Decreased Ptgs2 expression in intestinal polyps was also observed in ApcMin/+Clec7a−/− mice, and its expression was only detectable in CD45+ leukocytes, but not in EpCAM+ epithelial cells, in both polyps and non-polyp tissues." (PMID 36932082, 2023).
psoriasis (2 papers, 2022 to 2025). An autoimmune condition characterized by red, well-delineated plaques with silvery scales that are usually on the extensor surfaces and scalp. "The expression level of EPCAM demonstrated moderate accuracy (0.7 < AUC < 0.9) in distinguishing between the Psoriasis and Control." (PMID 40557155, 2025). "Notably, partial LCs expressed a higher level of Ly6C, along with lower levels of langerin and EpCAM, indicating that monocyte-derived inflamed LCs were repopulated to psoriasis-like skin, which were consistent with previous reports." (PMID 35801590, 2022).
seminoma (2 papers, 2020 to 2024). A radiosensitive malignant germ cell tumor found in the testis (especially undescended), and extragonadal sites (anterior mediastinum and pineal gland). "CD133, which combined with EpCAM can be indicative for cancer stem cells, is expressed to high levels on the seminoma cell line TCam-2 and the EC lines GCT27 and NCCIT." (PMID 32438548, 2020).